IL6 (interleukin 6)
Diseases named in the same sentence as IL6 in open-access papers (continued):
Sharing a sentence is not in itself a finding about the gene and the disease.
dental caries (19 papers, 2018 to 2026). The decay of a tooth, in which it becomes softened, discolored, and/or porous. "Based on these conclusions, general and pediatric dentists should consider incorporating regular salivary IL-6 assessments as part of their diagnostic and monitoring protocols for children with dental caries." (PMID 40002706, 2025). "In support of this conclusion, a very recent study has shown that IL-6 is correlated to an active state of dental caries and associated with infectious consequences." (PMID 33202858, 2020). "Our findings align with global research, revealing a strong association between IL-6 levels and the severity and extent of carious lesions, suggesting that reducing IL-6 may alleviate inflammation related to dental caries." (PMID 40002706, 2025). "Limited research has explored the correlation between salivary IL-6 and dental caries, particularly in the context of ECC and RC." (PMID 40002706, 2025). "This study also found that the levels of salivary IL-6 increase with increases in the severity and number of dental caries activity in these children." (PMID 40002706, 2025). "Statistical analyses were conducted to compare salivary IL-6 levels between the study and control groups of each RC and ECC group and a test was also performed to assess the relationship between salivary IL-6 levels and the severity of dental caries." (PMID 40002706, 2025). "Future studies should include larger populations and a wider range of clinical and biochemical measures to better understand the role of salivary IL-6 in dental caries and to develop more targeted oral health strategies." (PMID 40002706, 2025). "Future research should build on these findings by incorporating diverse populations and a broader range of variables to refine oral health interventions and enhance our understanding of IL-6’s role in dental caries." (PMID 40002706, 2025). "Elevated values of pro-inflammatory cytokines IL-6, IL-8, and TNFα in saliva are found in people with dental caries and chronic stomatitis." (PMID 39684489, 2024). "A meta-analysis was performed using a random-effects model to evaluate the association between dental caries/health, and the concentration of TNF-α, IL-6 and IL-8." (PMID 39026257, 2024). "IL-6 was the most prevalent cytokine in the saliva of children and young adults with active dental caries." (PMID 39026257, 2024). "In silico network pharmacology analysis elucidated proteins like ESR1 and IL6 to be majorly involved in biological pathways of dental caries, which also interact with the protective ability of P. betle." (PMID 36557738, 2022). "On the contrary, IL-6 is correlated to dental caries, especially when caries are in an active state and associated to infectious consequences." (PMID 31892186, 2019). "Several studies showed a significant correlation between IL-6 salivary levels and dental caries, thus supporting the concept that caries disease is a chronic inflammatory condition." (PMID 31892186, 2019). "A distinct bacterial community structure and a differential expression of innate immune responses were observed in dental caries of Mexican individuals, with 2 genera, Olsenella and Parascardovia, exclusively found in moderate caries, and IL1β, IL6 and CXCL8 being overexpressed in dental caries." (PMID 36569197, 2022). "Previous studies have shown that salivary IL-6 levels decrease with improved oral hygiene, supporting earlier findings that cytokines like tumor necrosis factor-alpha (TNF-α), IL-6, and interleukin-8 (IL-8) are closely associated with the progression of dental caries." (PMID 40002706, 2025). "The meta-analysis revealed that there are significant differences between the levels of IL-6 and TNF-α in saliva of children with active dental caries compared to their control groups." (PMID 39026257, 2024). "The findings suggest that IL-6 and TNF-α levels may have potential as complementary biomarkers for assessing dental caries severity." (PMID 39026257, 2024).
dental caries (continued). "Our study did not confirm any correlation between dental caries extension and s-IgA and IL-6 levels." (PMID 31892186, 2019).
latent infection (19 papers, 2012 to 2025). "The minor (A) allele of IL6 rs62449495 appeared to protect against progression from latent infections to active HAT and against the development of active HAT by controls but these associations did not remain significant after Bonferroni correction." (PMID 29059176, 2017). "An association was observed at IL6 rs1818879, indicating that subjects with latent infections carrying the A allele had a lower risk of progressing to active HAT (p = 0.0001, OR = 0.39, CI95 = [0.24–0.63], BONF = 0.0034)." (PMID 28827791, 2017). "A new association was found between IL6 rs1818879 and a reduced risk of progressing from latent infection to active HAT." (PMID 28827791, 2017). "Its latent infection continuously activates the immune system, leading to elevated levels of pro-inflammatory cytokines such as interleukin-6 (IL-6) and tumor necrosis factor-α (TNF-α) in serum, thereby inducing a state of “inflammaging”." (PMID 41312362, 2025). "Cytokine expression profiles (IL-2, IL-4, IL-6, and IL-10) were analyzed in the latent infection model using flow cytometry." (PMID 40388758, 2025). "The Chlamydia is characterized by the latent infection of the body and the continuous secretion of cytokines, such as Tumor necrosis factor, interleukin (IL)-1β, and IL-6." (PMID 37660043, 2023). "KSHV continually evades the innate immune response using several approaches, like suppressing TGF-β signaling, activation of NF-κB response genes and encoding trace amounts of v-IL6, a truncated version of human IL-6, during latent infection." (PMID 28715488, 2017). "IL6 rs1818879 allele A (p = 0.0001, OR = 0.39, CI95 = [0.24–0.63], BONF = 0.0034) was associated with a lower risk of progressing from latent infection to active disease." (PMID 28827791, 2017). "IL6 plasma levels were found to be significantly higher in individuals with latent infection from Guinea as compared to controls or HAT patients." (PMID 28827791, 2017). "As previously observed, latent infection of control mice with MHV68 was associated with an increase in circulating levels of TNFα, IL-6, IL-12 and IFNγ compared with uninfected mice." (PMID 25599590, 2015). "There were suggestive associations at three loci in IL6 and TNFA in the comparison between active cases and controls, one SNP in each of APOL1, MIF and IL6 in the comparison between latent infections and active cases and seven SNP in IL4, HLA-G and TNFA between latent infections and controls." (PMID 29059176, 2017). "The main findings of our study are that the A allele of IL6 rs1818879 and the G allele of APOL1 G1 appear to be associated with a higher risk of developing a latent infection but a lower risk of progressing from latent infection with undetectable parasitaemia to active disease." (PMID 28827791, 2017). "However, during latent infection decreased levels of IL-6 and elevated levels of IL-10 have been reported which may be the reason for the lower expression of APPs in latently infected individuals." (PMID 26241963, 2015). "Regardless of T-cell activation, the study also indicates that IL-6, IL-10, and tumor necrosis factor-alpha levels increase during HCMV latent infection." (PMID 40388758, 2025). "In the HCMV latent infection model, PHA group, T-cell group, and FK506 group exhibited significantly increased interleukin (IL)-6, IL-10, and tumor necrosis factor-alpha secretion." (PMID 40388758, 2025). "It seems that CD is the result of a chronic low-grade inflammatory process triggered by latent infection with HHV-8, which leads to lymphoid system hyperplasia and also stimulates secretion of interleukin-6 (IL-6)." (PMID 27313621, 2016). "A pertinent question is, then, why the increases in IL-6 observed during experimental latent infection of monocytes with the miR-UL148D deletion virus does not, in itself, induce reactivation of latently infected monocytes." (PMID 27491954, 2016).
latent infection (continued). "Although our model does not represent a classical latent infection, we hypothesized that IL-6 would also promote HCMV transcription during a chronic infection." (PMID 25549333, 2014). "Therefore, Il6 appears as an important inflammatory cytokine mediating T. b. gambiense response and suggest that IL6 could play a role in the phenomenon of latent infections without parasitological confirmation." (PMID 28827791, 2017). "Our experimental findings demonstrate significant upregulation of IL-6, IL-10, and TNF-α in the latent infection model, independent of T-cell activation status." (PMID 40388758, 2025).
Lewis lung carcinoma (19 papers, 1993 to 2025). "To investigate the regulation of Pck1 and Pdk3 by IL-6 in vivo, we compared B6 mice injected with Lewis lung carcinoma (LLC) cells that were either engineered to express IL-6 or to lack IL-6 expression." (PMID 40275022, 2025). "Lewis lung carcinoma (LLC) activated macrophage to produce IL-6 and TNF-а through activation of TLR2 and TLR6." (PMID 27336891, 2016). "In accordance with other studies using the Lewis lung carcinoma, we observed a systemic pro-inflammatory condition as characterized by elevated serum levels of Il-6 and TNF-α." (PMID 21637823, 2011). "This involvement of IL-6 in the in vivo antitumor effect of a natural product coincides with what was observed after oral administration of 50 mg/kg of curcumin for 20 days to C57BL/6 mice implanted with Lewis lung carcinoma." (PMID 38137888, 2023). "Interestingly, Lewis lung carcinoma cells secrete extracellular vesicles containing interleukin-6 that induced lipolysis in 3T3-L1 cells via the STAT3 pathway." (PMID 37316878, 2023). "The expression level of interleukin-6 affects the cellular sensitivity to PDT, and the combination of PDT and interleukin-6 may serve as a novel strategy for the therapy of Lewis lung carcinoma." (PMID 30717818, 2019). "Moreover, FLP also reduces serum TNF-α, IL-1β, and IL-6 level in a Lewis lung carcinoma xenograft mouse." (PMID 26597177, 2015). "For example, Lewis lung carcinoma (LLC) cells secrete factors which activate TLR2 in murine macrophages, mediating IL-6 and TNFα production and inducing lung inflammation." (PMID 33922955, 2021). "Using the Lewis lung carcinoma (LLC) model, we show that tumor growth induces a progressive increase in peripheral inflammation as observed by elevated interleukin-6 (IL-6)." (PMID 30439993, 2018). "MEKi selumetinib has been previously observed to reduce IL-6 levels in a Lewis lung carcinoma model although it did not protect against cachexia." (PMID 33245731, 2020). "To test whether this JAK-STAT-mediated lipid-autophagy pathogenic axis is conserved, we employed a mouse IL-6 tumor model: C57BL/6 mice bearing Lewis lung carcinoma (LLC) tumors engineered either to secrete IL-6 (LLC+IL-6) or not (LLC)." (PMID 41256541, 2025).
myelodysplastic syndrome (19 papers, 2013 to 2025). A clonal hematopoietic disorder characterized by dysplasia and ineffective hematopoiesis in one or more of the hematopoietic cell lines. "In support of a role of TET2 in the regulation of inflammatory reactions in human cells, TET2 mutations in human macrophages prepared from bone marrow of patients with myelodysplastic syndromes were associated with increased induction of IL6 upon LPS stimulation." (PMID 35011643, 2021). "Soluble cytokines such as tumor necrosis factor (TNF), interferons (IFNs), and interleukin 6 (IL6) have been linked to hematologic neoplasms related to aging, including myeloproliferative neoplasms (MPN), myelodysplastic syndromes, and AML33–35." (PMID 37730831, 2023). "Noteworthy, a previous study evaluated serum levels of TNF-α, IL-6, and IL-10, in diagnostic samples obtained from patients with AML or high-risk myelodysplastic syndromes." (PMID 23616009, 2013). "In a murine model, local rhBMP-2 application was shown to enter the bloodstream, leading to the development of hepatic tumors due to the proliferation of myelodysplastic syndrome (MDS) cells and increased secretion of IL-6." (PMID 41226759, 2025). "Siltuximab, a chimeric anti-IL-6 monoclonal antibody, did not reduce RBC transfusions in transfusion-dependent patients with low- and intermediate-1-risk myelodysplastic syndrome." (PMID 26491227, 2015). "IL-1, IL-6, and TNF were recently shown to promote deregulation of erythropoietin with resultant anemia in acute myelogenous leukemia (AML) and myelodysplastic syndromes (MDS)." (PMID 26538823, 2015).
pheochromocytoma (19 papers, 2011 to 2025). "In pheochromocytoma surgery, inflammatory cytokines, such as catecholamines and IL-6, have been implicated in the development of perioperative fever." (PMID 38637748, 2024). "We present a first case report of an IL-6-producing pheochromocytoma associated with von Hippel Lindau (vHL) disease." (PMID 38389627, 2024). "Several reports have shown that fever of unknown origin and systemic inflammatory syndrome were associated with IL-6 producing pheochromocytoma, which tended to have a larger tumor volume as well as an elevated risk of pheochromocytoma multisystem crisis." (PMID 33795528, 2021). "In IL-6-secreting pheochromocytomas, extreme CRP and fibrinogen levels have been observed alongside very high ESRs (ESR > 100 mm/hour)." (PMID 41357012, 2025). "Fibrinogen, being an acute-phase protein, is frequently elevated in active pheochromocytoma (especially if there is an IL-6-mediated response)." (PMID 41357012, 2025). "Studies showed that pheochromocytoma tumors can secrete hormones other than catecholamines, including cytokines, mainly interleukin (IL)-1, IL-6, and tumor necrosis factor alpha (TNF-α)." (PMID 41477390, 2025). "MALAT1 was also proven to upregulate pro-inflammatory factors in poststroke mice, and MALAT1 knockdown partially reduced the levels of TNF-α, IL-6, and IL-1β in mouse pheochromocytoma cell lines after oxygen and glucose deprivation/reperfusion." (PMID 40869277, 2025). "Pheochromocytomas occasionally lead to the production of cytokines, such as IL-6, or provoke an inflammatory acute-phase reaction in the host." (PMID 41357012, 2025). "Our findings contribute to the understanding of IL-6-producing pheochromocytomas and their distinct clinical characteristics." (PMID 38389627, 2024). "Administering doxazosin lowered the CRP and IL-6 levels, then IL-6-producing pheochromocytoma was suspected, and adrenalectomy was performed." (PMID 37908215, 2023). "Herein, we present a case of pheochromocytoma whose clinical manifestations changed, and IL-6 levels elevated over time." (PMID 37908215, 2023). "Functioning forms such as mimicking pheochromocytoma, Conn syndrome and inflammatory IL-6 secretion were rarely described in the literature." (PMID 37959390, 2023). "We report perioperative anesthetic management of a rare interleukin-6 (IL-6)-producing pheochromocytoma." (PMID 34117557, 2021). "In summary, we conducted the perioperative anesthetic management of a patient with an IL-6-producing pheochromocytoma." (PMID 34117557, 2021). "We performed perioperative and anesthetic management for a patient with an IL-6-producing pheochromocytoma." (PMID 34117557, 2021). "To date, 39 cases with IL-6 producing pheochromocytoma and three cases with IL-6 producing paraganglioma have been reported." (PMID 33715142, 2021). "For patients with IL-6-producing pheochromocytoma, the preoperative administration of NSAIDs and alpha- and beta-blockers reportedly improves inflammation by decreasing or normalizing serum IL-6 levels." (PMID 34117557, 2021). "The combination of pheochromocytoma with persistent fever and elevated inflammatory markers raised the suspicion of IL-6 production." (PMID 33715142, 2021). "The conventional pheochromocytoma strategy allowed surgical removal of an IL-6-producing pheochromocytoma under general anesthesia." (PMID 34117557, 2021). "Two case reports showed that naproxen was effective in treating fever in patients with IL-6 producing pheochromocytoma." (PMID 33715142, 2021). "Our patient had slightly increased morning serum fasting cortisol (28.5 μg/dL, normal 5–25) and urinary cortisol (435 μg/24 hours, normal 70–320), as previously observed in a patient affected by IL-6-producing pheochromocytoma." (PMID 27579040, 2016). "Pheochromocytomas are able to produce a variety of biologically active neuropeptides, hormones other than catecholamines, and cytokines, mainly IL-1, IL-6, and TNF-α." (PMID 27579040, 2016).
pheochromocytoma (continued). "Beyond the common increased IL6 and sB7.2 expression levels displayed by both tumor entities compared to HVs, pheochromocytomas showed heightened MCP1, sPD-L1 and sCD25 levels, while paragangliomas exhibited reduced sPD-L2 expression with increased levels of sLAG3 and Galectin-9." (PMID 40038821, 2025). "By analogy, a pheochromocytoma that triggers high IL-6, or an acute-phase response, could lead to a similar decrease in protein S activity." (PMID 41357012, 2025). "Few studies have reported IL-6-producing pheochromocytoma whose underlying mechanism has not been elucidated." (PMID 37908215, 2023). "IL-6-producing pheochromocytoma should be considered in patients with adrenal tumors and fever of unknown origin." (PMID 37908215, 2023). "Indeed, the treatment of ischemic pheochromocytoma cells with mesenchymal stem cells produces therapeutic effects due to IL-6 and vascular endothelial growth factor secretion." (PMID 31010132, 2019). "In addition, IL-6 has relevance in clinical management because resection of IL-6-secreting pheochromocytoma is followed by complete resolution of both fever and other inflammation-associated signs." (PMID 27579040, 2016). "To date, several cases of IL-6-producing pheochromocytomas have been reported." (PMID 27579040, 2016). "In addition to secreting the catecholes dopamine, epinephrine and norepinephrine, numerous other hormones have been isolated from pheochromocytomas including adrenocorticotropin, vasoactive intestinal peptide, neuropeptide Y, IL-6, calcitonin, and chromogranin A." (PMID 21843357, 2011). "In accord with previous case reports, pheochromocytoma must be considered in the differential diagnosis of FUO, and the assay of serum IL-6 levels emerges as a precious marker in the laboratory workup." (PMID 27579040, 2016). "We compared the current case with other cases of pheochromocytoma that presented neither elevated serum IL-6 nor high fever." (PMID 38389627, 2024). "In this case series, three patients with IL-6 producing PPGL are described, including a patient with multiple paragangliomas with lesions suspicious for metastases, a patient with head neck paragangliomas and a patient with a large pheochromocytoma." (PMID 33715142, 2021). "These are not found in pheochromocytomas that produce only catecholamines and appear to be specific to IL-6-producing pheochromocytomas." (PMID 34117557, 2021). "Although FUO has been observed among both children and adults with pheochromocytoma, to the best of our knowledge this is the first case reporting a patient with IL-6-producing, noncatecholamines secreting, pheochromocytoma presenting as FUO." (PMID 27579040, 2016). "In addition to catecholamines, pheochromocytomas and paragangliomas (PPGL) may secrete interleukin-6 (IL-6)." (PMID 33715142, 2021). "In addition, serum IL-6 (78.8 pg/mL [normal range < 4]) was elevated, while IL-1β (10 pg/mL) and tumor necrosis factor-alpha (TNF-α; 1.17 pg/mL) levels were normal, which led us to diagnose an IL-6-producing pheochromocytoma." (PMID 34117557, 2021). "Although the effectiveness of nonsteroidal anti-inflammatory drugs and alpha-adrenergic receptor blockers in reducing inflammatory symptoms has been shown in some patients with IL-6-producing pheochromocytoma, our patient did not achieve fever remission through the use of both aspirin and doxazosin." (PMID 27579040, 2016).